MEG9 (maternally expressed 9)
Synonyms: LINC00584; C14orf89; NCRNA00225; MIR381HG
Gene: Long non-coding RNA gene on chromosome 14 (101,042,908 to 101,072,937, forward strand). Ensembl gene ENSG00000223403.
Gene Ontology:
Biological process: miRNA-mediated post-transcriptional gene silencing
Cellular component: RISC complex
Diseases named in the same sentence as MEG9 in open-access papers:
MEG9 is named in the same sentence as 22 diseases in open-access papers, as found by Europe PMC text mining. Sharing a sentence is not in itself a finding about the gene and the disease. The quoted sentences say what the papers report.
hepatocellular carcinoma (2 papers, 2022 to 2023). A malignant tumor that arises from hepatocytes. "In addition, MEG9 was significantly associated with hepatitis B virus (HBV) infection status in hepatocellular carcinoma, and epidermal growth factor receptor (EGFR) status in adenocarcinoma patients with non-small-cell lung cancer (NSCLC)." (PMID 37822927, 2023).
epilepsy (1 paper, 2025). A brain disorder characterized by episodes of abnormally increased neuronal discharge resulting in transient episodes of sensory or motor neurological dysfunction, or psychic dysfunction. "RNA-seq analysis of the iPSCs revealed that genes such as TTTY14, TBL1Y, MEG8, MEG9, BCORP1, and RPS4Y1 are not directly related to epilepsy." (PMID 40600194, 2025).
ischemia (1 paper, 2017). A hypoperfusion of the BLOOD through an organ or tissue caused by a PATHOLOGIC CONSTRICTION or obstruction of its BLOOD VESSELS, or an absence of BLOOD CIRCULATION. "Concerning MEG9 (Maternally Expressed 9), a lncRNA belonging to the MEG family, it has been described to be up-regulated upon hypoxia in human endothelial cells and in a model of mouse ischemia." (PMID 28611953, 2017).
lung adenocarcinoma (1 paper, 2018). A carcinoma that arises from the lung and is characterized by the presence of malignant glandular epithelial cells. "Moreover, DLK1 and MEG9 were significantly hypomethylated in patients with SCC (p<0.001 and p=0.01, respectively), while in lung adenocarcinoma, DLK1 was very similar to the control group (p=0.127)." (PMID 29435111, 2018).
nasopharyngeal carcinoma (1 paper, 2025). A carcinoma arising from the nasopharyngeal epithelium. "Similar to AGS-EBV-Z cells, reactivation of HONE1-Akata-Z and NPC43-Z nasopharyngeal carcinoma cell lines led to greatly increased levels of MEG8, MEG9, and MIR381HG (respectively)." (PMID 40674434, 2025). "We showed that the lncRNAs MEG9, MIR381HG, and MEG8, from which miR-409-3p, miR-381-3p and miR-370-3p are derived, were also upregulated upon reactivation in AGS and nasopharyngeal carcinoma cells lines and occurred very early in the lytic cycle at the time of BZLF1 expression." (PMID 40674434, 2025).
pancreatic adenocarcinoma (1 paper, 2022). "Ultimately, m6A-lncRNAs were used to determine a prognostic model of patients with pancreatic adenocarcinoma based on the expression values of three lncRNAs (AC092171.5, MEG9, and AC002091.1)." (PMID 35547245, 2022).
schizophrenia (1 paper, 2017). A major psychotic disorder characterized by abnormalities in the perception or expression of reality. "Interestingly, the downstream lncRNAs, Rtl1-AS and Meg9 harbor multiple clusters of miRNAs, many of which have been implicated in the pathophysiology of schizophrenia." (PMID 28515681, 2017).
somatotroph adenomas (1 paper, 2020). "AC126177.8, AC355974.2, LINC02475, MEG3, MEG9 and MiR7-3HG were the most significantly different lncRNAs in somatotroph adenomas." (PMID 33472171, 2020).
systemic lupus erythematosus (1 paper, 2024). An autoimmune multi-organ disease typically associated with vasculopathy and autoantibody production. "For example, lncRNAs, such as Hotair, LUST, anti-NOS2A, MEG9, SNHG4, TUG1, and NEAT1, have been found to be highly expressed in rheumatoid arthritis, while the expression of lnc-HSFY2–3:3 and lnc-SERPINB9–1:2 is reduced in systemic lupus erythematosus (SLE)." (PMID 38473997, 2024).
tumor (4 papers, 2015 to 2024). "LINC01605, SNHG20, LUCAT1, and ZNF337-AS1 had significantly high expression in tumor tissues, while MEG9, LINC01082, and DICER1-AS1 had high expression in ADJ tissues." (PMID 34544413, 2021). "MEG9 was established as a lncRNA with protective role in tumor angiogenesis, which action is induced by DNA damage." (PMID 33572862, 2021). "Along with MEG3, maternally expressed non-protein-coding RNA 9 encoded by MEG9 gene, plays a protective role in tumor angiogenesis in response to DNA damage." (PMID 33572862, 2021). "Eight (lincRNA-VLDLR, MEG9, H19 antisense, ncR-uPAR, NEAT1 (family), LUST, UM9-5, and HOTAIR) were significantly down-regulated in HCC tumor compared to non-tumor tissues at a significance level of p < 0.05." (PMID 26378581, 2015).
cancer (3 papers, 2018 to 2024). A tumor composed of atypical neoplastic, often pleomorphic cells that invade other tissues. "Infection with P. aeruginosa has been shown to suppress the expression of lncRNAs maternally expressed 9 (MEG9) and bladder cancer-associated transcript 1 (BLACAT1) in bronchial epithelial cells." (PMID 38542512, 2024). "Among them, MEG9 could protect endothelial cells from DNA damage-induced cell death and predict cancer prognosis through the PI3K-AKT signaling pathway." (PMID 37822927, 2023). "In the case of MEG8 and MEG9 lncRNAs, their functions in cancer remain unknown." (PMID 29435111, 2018).
adenocarcinoma (2 papers, 2019 to 2023). A common cancer characterized by the presence of malignant glandular cells. "According to the association analysis for EGFR mutation in patients with adenocarcinoma (n = 108, EGFR mutant = 64), we found 159 suggestive DMPs and six significant DMPs (cg09245319, cg17183999 [USP7], cg06366994 [CPE], cg24992236 [MEG9], cg22144719, and cg22448179 [EGFR])." (PMID 31450665, 2019).
infection (2 papers, 2017 to 2024). The state of being infected such as from the introduction of a foreign agent such as serum, vaccine, antigenic substance or organism. "Thus, the pattern of expression found by in silico analysis for MEG9 and BLACAT1 was confirmed with a significant down regulation at 2 and 6 h post-infection, respectively." (PMID 28611953, 2017). "In our study, MEG9 was found dramatically down-regulated 2 h post-infection compared to the non-infected status (0 h) in CF cells." (PMID 28611953, 2017).
neurodegenerative disease (1 paper, 2024). A disorder of the central nervous system characterized by gradual and progressive loss of neural tissue and neurologic function. "MEG9 has been recently reported to be downregulated in AD hippocampus and involved in the pathogenesis of autoimmune and neurodegenerative diseases." (PMID 39086756, 2024).
neurological diseases (1 paper, 2025). "Specifically, we chose the genes TTTY14, TBL1Y, MEG8, MEG9, BCORP1, and RPAS4Y1 for analysis, all of which were found to be unrelated to neurological diseases." (PMID 40600194, 2025).
MEG9 also shares sentences with these, for which no sentence is quoted: Burkitt lymphoma (1 paper); glioblastoma (1); hepatitis B virus (1); infarction (1); myocardial infarction (1); non-small cell lung carcinoma (1); rheumatoid arthritis (1).